PIP4P1 (phosphatidylinositol-4,5-bisphosphate 4-phosphatase 1)
Description:
Catalyzes the hydrolysis of phosphatidylinositol-4,5-bisphosphate (PtdIns-4,5-P2) to phosphatidylinositol-4-phosphate (PtdIns-4-P). Does not hydrolyze phosphatidylinositol 3,4,5-trisphosphate, phosphatidylinositol 3,4-bisphosphate, inositol 3,5-bisphosphate, inositol 3,4-bisphosphate, phosphatidylinositol 5-monophosphate, phosphatidylinositol 4-monophosphate and phosphatidylinositol 3-monophosphate. Regulates lysosomal positioning by recruiting JIP4 to lysosomal membranes, thus inducing retrograde transport of lysosomes along microtubules. Contributes to assembly of the V-ATPase complex in lipid rafts of the lysosomal membrane and to subsequent amino acid-dependent activation of mTORC1. May play a role in the regulation of cellular cholesterol metabolism.
Synonyms: C14orf9; TMEM55B; MGC26684
Tractability: Antibody: UniProt places it where antibodies can reach, with medium confidence; UniProt predicts a signal peptide or a membrane-spanning region; its Gene Ontology location is reachable by antibodies, with medium confidence. PROTAC: ubiquitination databases record sites on it.
Gene: Protein-coding gene on chromosome 14 (20,457,681 to 20,461,617, reverse strand). Ensembl gene ENSG00000165782.
Subcellular location: Late endosome membrane; Lysosome membrane; Cytoplasmic vesicle, phagosome membrane; Cell membrane
Pathways (Reactome):
Metabolism: Synthesis of PIPs in the nucleus
Gene Ontology:
Molecular function: phosphatidylinositol-4,5-bisphosphate 4-phosphatase activity; protein binding
Biological process: cholesterol metabolic process; lysosome localization; phosphatidylinositol dephosphorylation; positive regulation of TORC1 signaling; response to sterol depletion; phospholipid metabolic process; proton-transporting V-type ATPase complex assembly
Cellular component: late endosome membrane; lysosomal membrane; nucleoplasm; phagocytic vesicle membrane; plasma membrane
Genetic constraint (gnomAD): Loss-of-function variants: 14 observed, 31.39 expected, observed/expected ratio (o/e) 0.45, 90% interval 0.29 to 0.7. The upper end of that interval is the gene's LOEUF score, 0.7, which puts it in group 2 of 6, group 1 being the genes least tolerant of losing a copy. Missense variants: 289 observed, 357.58 expected, observed/expected ratio (o/e) 0.81, 90% interval 0.73 to 0.89. Synonymous variants: 132 observed, 132.08 expected, observed/expected ratio (o/e) 1, 90% interval 0.87 to 1.15.
Homologues: Orthologues: chimpanzee PIP4P1 (100% identical), macaque PIP4P1 (100% identical), pig PIP4P1 (99% identical), dog PIP4P1 (99% identical), guinea pig PIP4P1 (99% identical), mouse Pip4p1 (97% identical), rat Pip4p1 (96% identical), tropical clawed frog pip4p1 (80% identical), zebrafish pip4p1a (71% identical), zebrafish pip4p1b (66% identical), Drosophila melanogaster CG6707 (44% identical), Caenorhabditis elegans pipp-4P (38% identical), and 1 more. Paralogues in human: PIP4P2 (52% identical).
Diseases named in the same sentence as PIP4P1 in open-access papers:
PIP4P1 is named in the same sentence as 9 diseases in open-access papers, as found by Europe PMC text mining. Sharing a sentence is not in itself a finding about the gene and the disease.
PIP4P1 shares sentences with these, for which no sentence is quoted: atherosclerosis (1 paper); bladder cancer (1); Hepatic steatosis (1); hepatoma (1); liver fibrosis (1); Meniere disease (1); metabolic dysfunction-associated steatohepatitis (1); Parkinson disease (1); steatosis (1).